PRL (prolactin)
Diseases named in the same sentence as PRL in open-access papers (continued):
Sharing a sentence is not in itself a finding about the gene and the disease.
sexual dysfunction (continued). "Compared with participants without sexual dysfunction, participants with sexual dysfunction were more likely to be female and advanced in age and more likely to have had concomitant antidepressant, longer durations of illness, and higher prolactin levels." (PMID 34421613, 2021). "Little is known about the possible use of the prodopaminergic effects of amantadine in patients treated for schizophrenia with sexual dysfunction without concomitant elevation of prolactin." (PMID 34681171, 2021). "The serum prolactin levels were significantly higher in patients with sexual dysfunction than in those without." (PMID 29209406, 2017). "In this sexual dysfunction group, the mean serum prolactin level (21.43 ± 31.57 μg/mL) was significantly higher than in subjects who did not check any items (non-sexual dysfunction group; 9.18 ± 9.66 μg/mL) (P = 0.01647)." (PMID 29209406, 2017). "In other studies, selegiline and cyproheptadine were not effective for sexual dysfunction and one small double blind trial has found benefits with sildenafil for sexual dysfunction but this was not focused on prolactin as a culprit." (PMID 23968123, 2013). "Many studies have showed that excess or lack of sexual hormones, such as prolactin and testosterone, induced the sexual dysfunction in humans." (PMID 20046395, 2009). "Similarly, patients with sexual dysfunction presented higher PRL as compared with no sexual dysfunction patients." (PMID 32373066, 2020). "As a hormone involved in reproductive behavior it could play a role in sexual dysfunction of uremia but treatment with bromocryptin could suppress prolactin but did not correct sexual dysfunction in hemodialysis patients of both genders." (PMID 29316724, 2018). "The relationship between antipsychotic drugs and sexual dysfunction is mediated in part by antipsychotic blockade of pituitary D2 receptors increasing prolactin secretion, although direct correlations have not been established between raised prolactin levels and clinical symptoms." (PMID 22937269, 2011).
prostate cancer (68 papers, 1999 to 2026). A primary or metastatic malignant tumor involving the prostate gland. "PRL has been associated with a number of different forms of cancer, among them human breast and prostate cancer." (PMID 34158080, 2021). "The locally high concentration of PRL may also contribute to inflammation as this hormone has been suggested to mediate inflammation in various pathological contexts, including association with prostate cancer inflammation." (PMID 31269779, 2019). "The key targeted genes were linked to the following pathways: PPAR signaling, thyroid cancer, prostate cancer, prolactin signaling, and bladder cancer." (PMID 40599803, 2025). "We further investigate the function of PRL in prostate cancer (PCa) and explored its downstream effects." (PMID 38341429, 2024). "Previous study showed that higher expression of prolactin (PRL) was found in CRPC samples compared with hormone-naive prostate cancer (HNPC) and benign prostatic hyperplasia (BPH) samples." (PMID 38341429, 2024). "Results regarding the involvement of PRL in prostate cancer are inconclusive; nevertheless, it has been shown that PRL plays a key role in the early carcinogenesis of the gland, while it does not have a significant role in the later stages of development." (PMID 36833950, 2023). "The prolactin (PRL) system has emerged as a relevant player in neoplasia, especially in breast and prostate cancers." (PMID 37208719, 2023). "Overexpression of PRL and/or PRLR were also described in glioblastoma, gynecological cancers, prostate cancer among other tumor types, reinforcing the notion of PRL:PRLR axis as a broad neoplastic feature providing proliferation and/or survival signaling." (PMID 37208719, 2023). "With prostate cancer, PRL overexpression contributes to increased hyperplasia of prostatic tissues, thereby elevating the risk for developing adenocarcinomas." (PMID 36714582, 2022). "We can see that Androstenedione is the major metabolite of both Prostate cancer and Prolactin signaling pathway." (PMID 36478867, 2022). "The proteins in cluster 1 also have connections with promoting male reproductive function by affecting “Prostate cancer”, “Endocrine resistance”, “Relaxin signaling pathway” and “Prolactin signaling pathway”." (PMID 33500463, 2021). "Human patients with benign prostatic hyperplasia or prostate cancer have higher blood levels of PRL." (PMID 34158080, 2021). "There are a variety of hormones and cytokines considered important growth factors for prostate cancer, one of which is the hormone, prolactin (PRL)." (PMID 33179012, 2020). "In previous work, we had observed that the selective prolactin receptor modulator, S179D PRL, sensitized prostate cancer cells in vitro to physiological concentrations of calcitriol through an ability to increase expression of the vitamin D receptor." (PMID 33179012, 2020). "Using prostate cancer cell lines in vitro, we have previously shown that S179D PRL sensitizes DU145 and PC-3 cells to the anti-tumor effects of physiological concentrations of calcitriol through its ability to increase expression of the VDR." (PMID 33179012, 2020). "Previous work showed a synergy between S179D PRL and calcitriol in the promotion of prostate cancer cell death in vitro." (PMID 33179012, 2020). "One would therefore predict additional benefits of S179D PRL in a clinical situation since then it would also interfere with the prostate cancer-promoting effects of circulating PRL." (PMID 33179012, 2020). "Since both calcitriol and S179D PRL induce apoptosis of prostate cancer cells, the relative number of apoptotic cells at the boundary between the acellular and viable regions of the tumor was assessed." (PMID 33179012, 2020). "The role of prolactin and prolactin receptor has been most well studied in breast and prostate cancer." (PMID 31795960, 2019).
prostate cancer (continued). "Reports have provided strong evidence regarding the role of PRL/STAT5 pathway in the progression of human prostate cancer via an autocrine/paracrine mechanism (for reviews." (PMID 31269779, 2019). "Studies of human prostate cancer specimens support a role for prolactin (PRL) signaling in disease progression and recurrence." (PMID 31269779, 2019). "The top five KEGG pathways observed were pathways in cancer, hepatitis B, pancreatic cancer, prolactin signaling pathway and prostate cancer." (PMID 31014274, 2019). "Prolactin signaling pathway including Sphingolipid signaling pathway, Apoptosis, Longevity regulating pathway, Cellular senescence, Prolactin signaling pathway, Hepatitis C, Measles, and Prostate cancer is the first cluster." (PMID 30013745, 2018). "PRL and expression of PRLR on tumor tissues have been strongly implicated in breast and prostate cancers for a considerable time via its mitogenic and angiogenic properties." (PMID 28223541, 2017). "Prolactin inhibits TRAIL-induced apoptosis in hormone (androgen)-insensitive PC3 prostate cancer cells." (PMID 28173834, 2017). "We also applied our methodology to two pathological animals models: prolactin transgene-driven benign prostatic hyperplasia and orthotopic implantation of human prostate cancer xenografts." (PMID 26391476, 2015). "In prostate cancer, treatment with the PRL inhibitor S179D PRL upregulated the expression of SF1b thus leading to upregulation of p21, a cell cycle inhibiting protein, and the vitamin D receptor known to promote differentiation." (PMID 21144038, 2010). "The role of prolactin (PRL) in prostate cancer had been investigated in some previous studies." (PMID 38341429, 2024). "These 233 altered metabolites in the colon content from the colonization group were significantly associated with six pathways: GABAergic synapse, synaptic vesicle cycle, prolactin signaling pathway, prostate cancer, alanine, aspartate and glutamate metabolism, and protein digestion and absorption." (PMID 39664059, 2024). "The collected data suggest that PRL, including that produced locally in the prostate gland, should be considered a promoter of benign and malignant prostate tumors, and the autocrine and paracrine mechanism itself should be considered a new therapeutic approach." (PMID 38370355, 2024). "However, it is worth mentioning a case reported by Costello, in which inhibition of pituitary PRL production with CAB was an effective treatment in a patient with advanced prostate cancer." (PMID 38370355, 2024). "Finally, Bioinformatics analysis showed that compared to control group, the metabolic pathways with significant differences in WAS group were as follows: endocrine resistance, tryptophan metabolism, prostate cancer and prolactin signaling pathway." (PMID 36478867, 2022). "On the basis of the results, one may assume the influence of hormones, particularly prolactin, on the development of prostate cancer." (PMID 35323711, 2022). "Compared with control group, there were remarkable differences in endocrine resistance (Androstenedione), tryptophan metabolism pathways (2-Aminophenol, 4-Hydroxy-2-quinolinecarboxylic acid), prostate cancer (Androstenedione) and Prolactin signaling pathway (Androstenedione) in WAS rats." (PMID 36478867, 2022). "prolactin)—play a significant role in prostate cancer development and progression." (PMID 35323711, 2022). "Similar inhibition of PRL-induced carboxypeptidase D was also seen in prostate cancer." (PMID 36714582, 2022). "It has been shown that PRL variants acting as competitive PRLR antagonists can efficiently down regulate PRLR signaling, cell survival, and/or proliferation in various breast or prostate cancer preclinical assays." (PMID 34358244, 2021).
prostate cancer (continued). "The results revealed that miR-203 targets were particularly enriched in signaling including pathways in cancer, proteoglycans in cancer, focal adhesion, Wnt, prolactin, FoxO and Ras signaling pathway, as well as some types of cancer including glioma, bladder, pancreatic, and prostate cancer and." (PMID 33059609, 2020). "In addition to effects via induction of the VDR, S179D PRL has additional anti-prostate cancer benefit derived from interruption of the autocrine PRL growth loop mediated through PRLRLF signaling." (PMID 33179012, 2020). "Upon examination of a series of 80 prostate cancer specimens, autocrine prolactin immunostaining was positive in 54% of samples and local prolactin levels positively correlated with both high Gleason scores and activation of Stat5a/b, the major downstream signaling protein from the PRLRLF to growth." (PMID 33179012, 2020). "Furthermore, by interrupting the PRL autocrine growth loop, S179D PRL delays the appearance and decreases the growth of human prostate cancer xenografts." (PMID 33179012, 2020). "The expression of PRL and PRLR has been reported to be higher in breast and prostate cancer than in their healthy counterparts and has been associated with increased risk of breast and prostate cancer and treatment resistance." (PMID 31862900, 2019). "Since circulating PRL levels are not correlated to prostate cancer risk, this suggests that the contribution of PRL signaling to prostate tumorigenesis mainly occurs through an autocrine/paracrine mechanism." (PMID 31269779, 2019). "Although prolactin has a well-known role in lactation, recent studies have reveal that the 16 kDa isoform derived from native prolactin has inhibitory effects on angiogenesis and tumorigenesis in breast and prostate cancers." (PMID 30045691, 2018). "We then apply this technique to two distinct prostate disease models: growth of the prostate in a prolactin-driven benign prostatic hyperplasia model, and growth of human prostate cancer orthotopic xenografts implanted in the anterior lobe of the mouse prostate." (PMID 26391476, 2015). "Indeed, antipsychotics that increase prolactin may have a significant impact on the likelihood of developing breast and prostate cancer over time." (PMID 36900794, 2023). "However, calcium channel blockade inhibits prolactin gene expression, inhibition of prolactin may be important in the treatment of advanced prostate cancer." (PMID 31614431, 2019). "Then, it is suggested that a serum PRL test could be useful to predict the beginning of prostate abnormal growing, even before the prostate-specific antigen appears in serum and much before prostate cancer symptoms occur." (PMID 16707016, 2006). "In breast and prostate cancers, CPD is upregulated by hormones including prolactin, estrogen, and testosterone, driving oncogenic effects through promoting NO generation and enhancing tumor cell survival." (PMID 41306918, 2025). "We have identified targets such as AKT1, TNF, IL6, STAT3, and CTNNB1 in Osthole’s inhibition of prostate cancer, along with pathways including the TNF signaling pathway, the Interleukin-6-17 (IL-6-17) signaling pathway, and the prolactin signaling pathway." (PMID 40978029, 2025). "GATA3 regulation happened in the early stage and the outcome of the prostate cancer at the late stage of tumor development that are related to genes MZF1, SREBF1, PRL, and DDIT3." (PMID 20025723, 2009). "The KEGG enrichment analysis revealed 141 potential pathways, and the 10 most significantly enriched pathways included prostate cancer, Janus kinase/signal transducer and activator of transcription (JAK/STAT) signaling, non-small cell lung cancer, prolactin signaling, lipid, and atherosclerosis." (PMID 40351419, 2025).
prostate cancer (continued). "The various signalling pathways that were identified include: PI3K-Akt, Prostate cancer, Ras, Chemokine, HIF-1, FoxO, sphingolipid, AMPK, VEFG, JAK-STAT, insulin, GnRH, oestrogen, prolactin, thyroid hormone, relaxin, progesterone-mediated oocyte maturation, and progesterone." (PMID 39114070, 2024). "In summary, the expression and functions of the down streaming signals of PRL in prostate cancer was not figured out thoroughly, and the role of PRL in mCRPC stage is unclear." (PMID 38341429, 2024). "RWPE-1 and prostate cancer (DU-145, PC-3 and ARCaP-M) cells and LT-2 and pancreatic cancer (MIA PaCa-2, AsPC-1 and PANC-1) cells were transfected with pGADD, pPEG, pGAPE, pT-GADD, pT-GADD1-1, pT-GADD2-2 and pT-GADD-2 along with PRL-TK for 48 h." (PMID 35326649, 2022). "PRL (endocrine or autocrine), acting via the PRLRLF in vivo, activates the Janus Kinase 2 - Signal Transducer and Activator of Transcription 5 (Jak 2-Stat5a/b) pathway, preventing apoptosis and allowing the survival of prostate cancer cells." (PMID 33179012, 2020). "Irrespective, the present work provides a possible explanation for the absence of prostate cancer development in Pb-PRL mice as we show that the prostates of these animals progressively lack STAT5 signaling with age." (PMID 31269779, 2019). "While some of these biological effects are also observed in Pb-PRL mice (e.g., cell survival, proliferation, and stemness), the latter mice do not develop prostate cancer despite strong STAT5 action." (PMID 31269779, 2019). "Besides, MOLBCH could regulate the male reproductive function by affecting “Prostate cancer”, “Endocrine resistance”, “Relaxin signaling pathway”, “EGFR tyrosine kinase inhibitor resistance” and “Prolactin signaling pathway”." (PMID 33500463, 2021). "Whatever the mechanisms driving the intrinsic decline of prostatic STAT5 signaling in Pb-PRL mice, the various genotype- and age-related phenomena observed in our study may shed light on possible outcomes of long-term pharmacological inhibition of STAT5 in prostate cancer context." (PMID 31269779, 2019). "The results of a recent study suggested that extracellular PRL enhanced NSCLC cell proliferation and promoted JAK2/STAT3 signaling activity through GHR, but not PRLR as previously reported in breast and prostate cancers." (PMID 34487971, 2021). "Another study, reported that treatment with PRL does not promote proliferation in PC3 and LNCaP cell lines derived from prostate cancer, but has shown a pro-apoptotic effect on the LNCaP cell line which responds to stimulation with androgens." (PMID 26346346, 2015).